LINC00333 (long independently transcribed non-coding RNA 333)
Synonyms: formerly NCRNA00333
Gene: Long non-coding RNA gene on chromosome 13 (84,562,364 to 84,563,236, forward strand). Ensembl gene ENSG00000233349.
Diseases named in the same sentence as LINC00333 in open-access papers:
LINC00333 is named in the same sentence as 1 disease in open-access papers, as found by Europe PMC text mining. Sharing a sentence is not in itself a finding about the gene and the disease.
LINC00333 shares sentences with these, for which no sentence is quoted: schizophrenia (1 paper).